GPR153 (G protein-coupled receptor 153)
Description:
Orphan receptor.
Synonyms: PGR1
Tractability: Small molecule: it belongs to a druggable protein family. Antibody: UniProt places it where antibodies can reach, with medium confidence; UniProt predicts a signal peptide or a membrane-spanning region; its Gene Ontology location is reachable by antibodies, with medium confidence.
Target class: Family A G protein-coupled receptor; Membrane receptor
Gene: Protein-coding gene on chromosome 1 (6,247,347 to 6,261,098, reverse strand). Ensembl gene ENSG00000158292.
Subcellular location: Cell membrane
Gene Ontology:
Molecular function: G protein-coupled receptor activity
Biological process: G protein-coupled receptor signaling pathway
Cellular component: membrane; plasma membrane
Genetic constraint (gnomAD): Loss-of-function variants: 27 observed, 30.51 expected, observed/expected ratio (o/e) 0.88, 90% interval 0.65 to 1.22. The synonymous counts are far from expectation, so gnomAD's model fits this gene poorly and the ratio says little. Missense variants: 839 observed, 723.05 expected, observed/expected ratio (o/e) 1.16, 90% interval 1.1 to 1.23. Synonymous variants: 405 observed, 337.62 expected, observed/expected ratio (o/e) 1.2, 90% interval 1.11 to 1.3.
Homologues: Orthologues: chimpanzee GPR153 (99% identical), macaque GPR153 (97% identical), mouse Gpr153 (88% identical), rat Gpr153 (88% identical), pig GPR153 (84% identical), guinea pig GPR153 (81% identical), dog GPR153 (65% identical), tropical clawed frog gpr153 (61% identical), zebrafish gpr153 (59% identical). Paralogues in human: GPR162 (44% identical).
Diseases named in the same sentence as GPR153 in open-access papers:
GPR153 is named in the same sentence as 4 diseases in open-access papers, as found by Europe PMC text mining. Sharing a sentence is not in itself a finding about the gene and the disease. The quoted sentences say what the papers report.
breast carcinoma (1 paper, 2020). "According to Kaplan–Meier plotter, low expression of FOSB, GPR153, and MYH4 is associated with poor RFS in breast cancer patients." (PMID 32679794, 2020).
ischemic stroke (1 paper, 2025). A stroke disorder caused by obstruction of blood flow to the brain, due to thrombotic (local blood clot formation) or embolic (due to a blood clot or other material traveling from another site) event. "However, our findings are currently limited to the murine models of ligation-induced neointima formation, EAE, and ischemic stroke, and further studies are required to determine the relevance of GPR153 in other vascular damage models." (PMID 40623996, 2025).
Stroke (1 paper, 2025). Sudden impairment of blood flow to a part of the brain due to occlusion or rupture of an artery to the brain. "Interestingly, a similar role of GPR153 was observed in endothelial cells (ECs), where loss of GPR153 resulted in reduced inflammatory gene expression and protected mice with EC-specific GPR153 deficiency in models of neuroinflammation and stroke." (PMID 40623996, 2025).
GPR153 also shares sentences with these, for which no sentence is quoted: medulloblastoma (1 paper).